EGFR (epidermal growth factor receptor)
Diseases named in the same sentence as EGFR in open-access papers (continued):
Sharing a sentence is not in itself a finding about the gene and the disease.
glioma (continued). "We speculate that the EGFR signaling pathway acts upstream of MAPK4 in glioma, and future work is aimed at determining whether MAPK4 is regulated by the EGFR signaling pathway." (PMID 36999945, 2023). "In our study, the lack of EGFR immunoreactivity was the only 100% sensitive marker of reactive gliosis, although with the lowest specificity, since only 31.9% (43/135) of all gliomas showed any immunoreactivity." (PMID 37568909, 2023). "Interestingly, most of these proteins are ECM molecules and contribute to the invasiveness of glioma cells, including FN1, TNC, LAMC1, COL1A1, EGFR, CDK6, and COL6A2." (PMID 37059730, 2023). "In addition to IDH1/2 mutation, MGMT promotor methylation, EGFR amplification, TERT promotor mutation, and CDKN2A/B homozygous deletion, we sought to elucidate the alterations of other potential molecular biomarkers that might provide clues for clinical decision-making in gliomas." (PMID 36998447, 2023). "Taken together, these results suggest that IFI30‐mediated EGFR/AKT/GSK3β/β‐catenin signaling not only promotes the EMT‐like phenotype by up‐regulating the expression of Slug, but also subsequently enhanced invasion and chemoresistance of glioma cells." (PMID 37408388, 2023). "We also performed IHC staining, utilizing PDGFRA antibody (OPC-like marker), EGFR antibody (AC-like marker) and HIF-1A antibody (MES-like marker) and confirmed the specific cell states are enriched in distinctive proteomic subsets of gliomas." (PMID 36720864, 2023). "The incidence of EGFR amplification and low Ki67 index between TERT mutant and wild-type GBMs was also no different, indicating a similar proliferative capacity of the TERT mutant and wild-type glioma cells." (PMID 37566174, 2023). "We observed high CD31, EGFR, and VEGFA expression predicted poor prognosis in glioma patients." (PMID 37534312, 2023). "For example, in a Phase 1 study of an EGFRvIII-specific CAR in GBM, a single dose of the CAR-T cells led to downregulation of the EGFR/EGFRvIII receptor, whereas IL13Ra2-specific CAR-T cells co-expressing IL-15 were potent against glioma but led to the rise of tumors with IL13Ra2 downregulation." (PMID 37420216, 2023). "In pediatric high-grade gliomas, which occur largely de novo, isocitrate dehydrogenase 1 (IDH1), epidermal growth factor receptor (EGFR), phosphatase and tensin homolog (PTEN), and other classic driver mutations and alterations identified in adult GBM are rare." (PMID 37109493, 2023). "Although many clinical trials aiming to study EGFR targeted therapies have been performed, none of them have reported promising clinical results when used in glioma patients." (PMID 37446288, 2023). "Of all analyzed IDH wildtype gliomas, 26% showed EGFR amplification, and among IDH mutated gliomas, none showed an EGFR amplification." (PMID 35453544, 2022). "Several factors, such as integrin, E-cadherin, EGFR, IGFR, Trk, TGF-β, the Hippo pathway, NF-κB, eEF-2 kinase, MOB2, hypoxia, acidosis, ROS, Hsp and protective autophagy, have been shown to induce anoikis resistance in glioma." (PMID 36046036, 2022). "Other examples of available anticancer agents that have been identified to exhibit potent anti-glioma effect at preclinical level include plicamycin an antineoplastic antibiotic agent, trametinib a MEK inhibitor, afatinib an EGFR inhibitor and topotecan a topoisomerase-I inhibitor." (PMID 35954371, 2022). "As a result, immunoaffinity against phospho-peptide GSHQIS[+80]LDNPDYQQDFFPK (EGFR phospho-site S1166) was detected in high-grade glioma (HGG) patient plasma but not in healthy donor plasma." (PMID 35563452, 2022).
glioma (continued). "At the molecular level, Bcan and its cleaved products are secreted by the tumor cells, and activate EGFR/mitogen-activated protein kinase (MAPK) signaling and fibronectin production in glioma cells to enhance cell adhesion, migration, and invasive characteristics." (PMID 35565337, 2022). "The results showed that when used individually, MMP9 and MUC4 tissue expression can predict clinical outcome in glioma patient diagnosis, which is not the case with EGFR." (PMID 36400876, 2022). "In a next step, we examined the EGFR copy number status in 10 lower grade gliomas for which we expected no EGFR copy number increase (samples 16–25)." (PMID 35361262, 2022). "They found that, unlike epithelial cell-derived carcinomas, PTPN12 in glioma, primarily derived from neural stem cells, suppressed migration/invasion but promoted growth and viability even though EGFR and HER2 are hyperphosphorylated." (PMID 36341348, 2022). "In addition, there are new drugs targeting epidermal growth factor receptor (EGFR) and mammalian target of rapamycin (mTOR) for the treatment of gliomas." (PMID 36605558, 2022). "A relatively high Q-score in EGFR amplified tissue reflected and summarized both high positivity and intensity of USP6L expression in this subset, as opposed to non-EGFR amplified glioma tissue." (PMID 35884836, 2022). "In general, EGFR interacts with members of the mucin family in cancer, and as such, MUC4 may physically interact with EGFR in a ligand-dependent manner, leading to downstream signalling and MMP9-mediated glioma initiation and progression." (PMID 36400876, 2022). "The classical glioma subtype in the Chinese population does not show consistent strong EGFR expression." (PMID 36350002, 2022). "Upregulated EGFR and its interaction with BCAR4 were proved in glioma cells in their study." (PMID 36081848, 2022). "Read and colleagues (2009) demonstrated that Drosophila glia and glial precursors, constitutive coactivation of EGFR-Ras and PI3K signaling leads to neoplastic, invasive cells that form transplantable tumor-like growths, replicating human glioma and animal glioma models." (PMID 36003330, 2022). "Analysis of LOH 1p/19q status and EGFR amplification showed increased copies of EGFR in gliomas without LOH 1p/19q using FISH and EPIC without being statistically significant (p > 0.05, Student’s t-test)." (PMID 35453544, 2022). "It was shown that glioma stem-like cells exposed to supramolecular fibers with IKVAV incorporated, undergo apoptosis via inhibition of focal adhesion kinase combined with inhibition of epidermal growth factor receptor (EGFR)." (PMID 36430214, 2022). "In turn, EGFR triggers the activation of signalling cascades impinging on signal transducer and activator of transcription 3 (STAT3), AKT, and the mitogen-activated protein kinases (MAPKS) ERK1/2, thereby promoting the oncogenic phenotype of glioma cells." (PMID 35269953, 2022). "Even in the new WHO Classification, there are cases that do not fit and are classified as NEC (Not Elsewhere Classified), e.g., IDH wt gliomas that do not exhibit EGFR amplification or TERTp or combined whole chromosomes +7/−10q." (PMID 35558510, 2022). "MMP9 and MUC4, but not EGFR, protein expression is correlated with increased glioma histological grades and IDH-WT genotype." (PMID 36400876, 2022). "Of IDH wildtype and TERT mutant gliomas, 58.13% were EGFR non-amplified and 41.87% were EGFR amplified." (PMID 35453544, 2022). "EGFR is an overexpressed and validated target in various cancers such as colorectal, gynecological and urological cancers, squamous cell carcinomas (SSC) of the head and neck, non-small cell lung cancer, renal and breast neoplasms and gliomas." (PMID 35269611, 2022). "Moreover, high GDF15 expression was significantly related to EGFR and chromosome 7 copy number amplification, as well as PTEN and chromosome 10 copy number reduction, which were both markers of poor prognosis for glioma." (PMID 34697897, 2022).
glioma (continued). "Considering what is known about increased EGFR and ANO expression in cancer, particularly in gliomas, further investigation into how calcium signalling may contribute to drug resistance and cellular plasticity in brain tumour progression is warranted." (PMID 36497413, 2022). "The last pathway includes gliomas without mutations in IDH gene, but with multiple genetic alterations, such as amplification or mutation of EGFR and loss of PTEN gene." (PMID 35756624, 2022). "The discrepancy of rCBV findings is likely due to the heterogeneous composition of gliomas in which EGFR-amplified and non-amplified tumor cells co-exist." (PMID 35626127, 2022). "Regarding the mechanism, we clarify that epidermal growth factor receptor (EGFR) signaling is regulated by GBP2, and also demonstrate that GBP2 interacts directly with kinesin family member 22(KIF22) and regulates glioma progression through KIF22/EGFR signaling in vitro and in vivo." (PMID 35436989, 2022). "Here, we performed an integrated comparative analysis of EGFR amplification in 34 glioma samples using standard fluorescence in situ hybridization (FISH) and Illumina EPIC Infinium Methylation Bead Chip and correlated results with molecular glioma hallmarks." (PMID 35453544, 2022). "Median R2’ was significantly higher in EGFR-amplified than non-amplified gliomas (6.36 ± 1.52 s−1 vs. 5.41 ± 1.12 s−1, p = 0.024)." (PMID 35626127, 2022). "EGFR-expressing glioma cells exhibit increased glutamate export, cystine uptake, and GSH biosynthesis, while targeted inhibition of SLC7A11 suppresses the antioxidant capacity, growth, and invasion of EGFR-overexpressing cancer cells." (PMID 36552652, 2022). "Furthermore, we found three EGFR and FGFR signaling feedback regulators common to all analyzed gliomas—SPRY4, ERRFI1, and RAB31—which can be used for creating new therapeutic strategies of suppressing the invasion and progression of gliomas." (PMID 36231068, 2022). "None of the 47 NF1-associated gliomas in this cohort had IDH1 or IDH2 mutation, EGFR amplification, TERT promoter mutation, or histone H3 p.G34 mutation." (PMID 35945463, 2022). "Interestingly, the expression of ETV6 is significantly positively related to the expression of EGFR and VEGF in glioma, especially in GBM." (PMID 36292767, 2022). "Moreover, enrichment analysis revealed that genes regulated by gliomas-specific long-range interactions are enriched in PI3K-AKT, Ras signaling pathways, and EGFR tyrosine kinase inhibitor resistance, all of which are associated with malignancy of GBM." (PMID 35521558, 2022). "Last but not least, our data on the principal role of EGFR in TF expression are consistent with corresponding studies of other designs in glioma, epidermoid, colorectal, breast and endometrial cancer cells." (PMID 34205482, 2021). "In young adult gliomas, we identified enrichment of KRAS and CCND2 amplifications with potential targeted treatment options, whereas later-onset LGG showed higher rates of actionable EGFR amplification." (PMID 34788626, 2021). "Although promising in preclinical studies, results obtained with oHSVs retargeted against HER2 and/or EGFR need to be critically evaluated since these receptors are not specific markers for glioma." (PMID 34578259, 2021). "In summary, the mRNA levels of EGFR and ERBB2 were higher in advanced and poorly differentiated gliomas; however, the mRNA levels of ERBB3 and ERBB4 were lower in advanced and poorly differentiated gliomas." (PMID 33892666, 2021). "Anti-EGFR ILs-DOX is another liposomal NP which is loaded with doxorubicin and has an antibody against EGFR as a targeting ligand and is being studied in patients with gliomas (NCT03603379)." (PMID 35582007, 2021). "The data indicate early treatment response of the bladder cancer cells, but not of the glioma cells though cell lines were killed following 213Bi-anti-EGFR-MAb treatment." (PMID 33737524, 2021).
glioma (continued). "Another biological target, the epidermal growth factor receptor (EGFR), is over-expressed on high-grade glioma, a tumor type that might be treated with BNCT." (PMID 33920126, 2021). "In this situation, glioma cells without EGFR protein expression experience no negative impact from EGFR inhibitors." (PMID 33435537, 2021). "Finally, the coexistence and unfavorable prognostic effects of EGFR amplification and CDKN2A alteration were validated using the Memorial Sloan Kettering Cancer Center (MSKCC) glioma datasets." (PMID 33959491, 2021). "Moreover, C-CBL, a RING-type ubiquitin E3 ligase, can lead to the downregulation of epidermal growth factor receptor (EGFR) and inhibit cell proliferation in glioma." (PMID 34445990, 2021). "On the other hand, although both the newly diagnosed and relapsing GBM samples displayed elevated EGFR expression compared with the grade I glioma samples, no significant change was found between the newly diagnosed and relapsing GBM samples." (PMID 34461927, 2021). "Furthermore, miR-181b is also a potential therapeutic target for glioma chemoresistance because it regulates the sensitivity of gliomas to TMZ by targeting BCL-2 and EGFR." (PMID 34745938, 2021). "On the contrary, CDH10 is largely expressed in glioma and its expression is higher in quiescent mouse neural stem cells compared with non-quiescent EGFR+ neural stem cells." (PMID 34885053, 2021). "WT EGFR is a TAA overexpressed in many gliomas and absent on normal CNS tissue, but it is expressed on normal peripheral tissues." (PMID 34868044, 2021). "EGFR-amplified tumor shows lower mean ADC values than EGFR-non-amplified gliomas, with an AUC of 0.75." (PMID 34422648, 2021). "In this situation, glioma cells fight back against EGFR inhibition by activating compensatory pathways independent of EGFR signaling." (PMID 33435537, 2021). "Ongoing clinical trials for fluorescence guided surgery of brain tumors using EGFR antibody or affibody (NCT03510208, NCT02901925 and NCT04085887) indicate the active exploration of molecular targeting strategy for detecting gliomas in both adults and children." (PMID 33707521, 2021). "Previous studies on Fyn’s role in cancer, including glioma, show that Fyn is activated via NRAS dependent and independent pathways through the oncogenic receptors EGFR, PDGFR, HGF/MET or RTK/RAS/PI3K to increase cell migration, proliferation and reduce cell death." (PMID 34168976, 2021). "EGFR amplification is often associated with high expression of EGFRvIII, a ligand-independent constitutively active mutant of EGFR, capable of persistently activating PI3K/v-Akt murine thymoma viral oncogene homolog (Akt) signaling pathway that promotes the survival of the glioma cells." (PMID 34440090, 2021). "Inhibitors of PDGFRβ, EGFR, or SDF-1αR (DMPQ, gefitinib, and burixafor, respectively) significantly reduced the stimulatory effect of MCM in all cell lines, confirming the key role of microglia-derived PDGFβ, EGF, and SDF-1α in glioma cell migration." (PMID 34944779, 2021). "Notably, reduction in the miR-7-5p expression contributes to the increase of EGFR expression and activation of the PI3K/AKT/c-Myc signaling pathway in the context of glioma." (PMID 33768139, 2021). "The effect of the chromosome 7p amplification on glioma patient prognosis is not clear, but generally glioma patients with EGFR or chromosome 7p amplification have shorter survival." (PMID 33981597, 2021). "In addition, we found that EGFR had higher transcription and protein expression levels compared with those for SLIT1 in gliomas characterized as WHO III in patients >40 years." (PMID 34123829, 2021). "In GB models, induction of oxidative stress by bis-chloroethylnitrosourea (BCNU/carmustine), an alkylating agent commonly used in the treatment of glioma, did not lead to c-Cbl phosphorylation or a decrease in EGFR activity." (PMID 33432111, 2021).
glioma (continued). "Benefitting from the recognition of glioma biomarkers such as O6-methylguananine–DNA methyltransferase (MGMT) and epidermal growth factor receptor, patients with glioma have been diagnosed as early as possible, but the overall 5-year survival rate is still far from satisfaction." (PMID 33414423, 2021). "In contrast to the negative results in newly diagnosed patients, anti-EGFR ADCs targeting glioma with EGFR over-expression or EGFRvIII showed clear signals of efficacy in patients with relapsed glioma after chemo-radiation." (PMID 34926242, 2021). "Finally, we validated the genetic connections and the prognostic significance of EGFR and CDKN2A alterations using the MSKCC glioma datasets." (PMID 33959491, 2021). "Cetuximab, an EGFR monoclonal antibody, when conjugated with fluorescent IRDye 800CW, fluoresces in the NIR, and has been shown in preclinical studies to be effective for glioma surgery." (PMID 34220688, 2021). "In the present study, using The Cancer Genome Atlas (TCGA), the Chinese Glioma Genome Atlas (CGGA), the Memorial Sloan Kettering Cancer Center (MSKCC), and Gene Expression Omnibus (GEO) datasets, the prognostic significance of EGFR and CDKN2A alteration was determined." (PMID 33959491, 2021). "EGFR-tyrosine kinase inhibitors (EGFR-TKIs), such as gefitinib, erlotinib, afatinib, and dacomitinib, have been studied in EGFR-altered gliomas but have yielded minimal to no clinical benefit and short durations of response." (PMID 35601813, 2021). "Thus, the inhibition of EGFR gene amplification and kinase activating mutants or the targeting of a unique EGFR epitope such as EGFRvIII with monoclonal antibodies for the inhibition of NF‐κB as well as tumour angiogenesis and growth may be rational strategies for the development of glioma therapy." (PMID 33300633, 2021). "In addition to being overexpressed in gliomas, knockdown of TRIM11 in primary glioma cultures was sufficient to significantly reduce levels of EGFR." (PMID 33432111, 2021). "The existence of truncated EGFR isoforms in glioma and its significance in therapeutic management are not clarified yet." (PMID 34356101, 2021). "Previous reports showed that miR-1231 could target EGFR and CACNA2D2 directly in glioma and embryonic kidney cells." (PMID 34650036, 2021). "Moreover, in human U87 glioma cells, GOLPH3 is bound to a complex that contains RAB5 and the epidermal growth factor receptor, although a direct interaction between GOLPH3 and RAB5 remains to be established." (PMID 32790781, 2020). "Therefore, it is critical to explore a potential effective targeting therapeutic strategy simultaneously targeting EGFR and MET to overcome TMZ resistance via E2F1 in glioma." (PMID 32001707, 2020). "CRNDE promoted malignant progression of glioma by STAT3 and EGFR." (PMID 33178271, 2020). "In our study, we demonstrated that miR-450a-5p regulated the autophagy occurrence in glioma by targeting EGFR-mediated PI3K/AKT/mTOR pathway, thereby regulating the proliferation, apoptosis, and migration of glioma cells and enhancing the sensitivity of glioma cells to gefitinib." (PMID 32820249, 2020). "Besides, we found that EGFR-positive expression was more common in the middle-age group, and the EGFR expression in IDH1-mut gliomas was more apparent." (PMID 32819307, 2020). "With nanoinhibitors as treatments on TMZ-resistant glioma cells, BIP-MPC-NP simultaneously attenuated p-EGFR and p-MET in cells with EGF and HGF incubation or without EGF and HGF incubation, and this attenuation was more significant than that of EBP-MPC-NP or MBP-MPC-NP group." (PMID 32001707, 2020).